Y_RNA (Y RNA )
Gene: Miscellaneous RNA gene on chromosome 2 (41,857,271 to 41,857,372, reverse strand). Ensembl gene ENSG00000207218.
Homologues: Orthologues: chimpanzee Y_RNA (98% identical), macaque Y_RNA (95% identical). Paralogues in human: RNY3 (85% identical), Y_RNA (85% identical), Y_RNA (84% identical), Y_RNA (83% identical), RNY3P1 (82% identical), RNY3P14 (82% identical), Y_RNA (82% identical), RNY3P16 (81% identical), RNY3P7 (81% identical), Y_RNA (81% identical), Y_RNA (80% identical), RNY3P2 (79% identical), and 93 more.